ZNF711 (ZFX family zinc finger ZNF711)
Description:
Transcription regulator required for brain development. Probably acts as a transcription factor that binds to the promoter of target genes and recruits PHF8 histone demethylase, leading to activated expression of genes involved in neuron development, such as KDM5C. May compete with transcription factor ARX for activation of expression of KDM5C.
Synonyms: CMPX1; ZNF6; ZNF4; ZNF5; dJ75N13.1; Zfp711; MRX97; MRX65; XLID97
Tractability: PROTAC: UniProt records ubiquitination sites on it; ubiquitination databases record sites on it.
Gene: Protein-coding gene on chromosome X (85,243,839 to 85,273,422, forward strand). Ensembl gene ENSG00000147180.
Subcellular location: Nucleus
Subcellular location (Human Protein Atlas): Nucleoplasm
Pathways (Reactome):
Gene expression (Transcription): Generic Transcription Pathway
Gene Ontology:
Molecular function: protein binding; sequence-specific DNA binding; zinc ion binding; DNA-binding transcription factor activity, RNA polymerase II-specific; RNA polymerase II cis-regulatory region sequence-specific DNA binding; DNA binding; metal ion binding
Biological process: positive regulation of DNA-templated transcription; positive regulation of transcription by RNA polymerase II; regulation of gene expression; regulation of transcription by RNA polymerase II; regulation of DNA-templated transcription
Cellular component: nucleus; chromatin
Gene-disease validity (ClinGen):
ClinGen rates the evidence that ZNF711 causes each of these diseases.
X-linked complex neurodevelopmental disorder (X-linked): Definitive. A complex neurodevelopmental disorder that is transmitted via X-linked inheritance, and is characterized by intellectual disability, autism and epilepsy.
Homologues: Orthologues: chimpanzee ZNF711 (100% identical), macaque ZNF711 (99% identical), pig ZNF711 (98% identical), dog ZNF711 (98% identical), rat Zfp711 (96% identical), mouse Zfp711 (94% identical), rabbit ZNF711 (86% identical), tropical clawed frog znf711 (82% identical), guinea pig ZNF711 (76% identical), zebrafish znf711 (70% identical). Paralogues in human: ZFX (59% identical), ZFY (58% identical), ZFAT (19% identical), PRDM15 (16% identical), ZBTB11 (16% identical), ZSCAN2 (14% identical), ZNF304 (14% identical), ZNF480 (14% identical), ZNF551 (14% identical), ZNF587B (14% identical), ZNF256 (14% identical), ZNF792 (13% identical), and 26 more.
Diseases named in the same sentence as ZNF711 in open-access papers:
ZNF711 is named in the same sentence as 28 diseases in open-access papers, as found by Europe PMC text mining. Sharing a sentence is not in itself a finding about the gene and the disease. The quoted sentences say what the papers report.
mental retardation (5 papers, 2013 to 2021). "ZF proteins like ZNF264 contribute to coordinated gene expression changes during brain aging and ZNF711 is reportedly associated with mental retardation and cognitive disability." (PMID 34494552, 2021). "The deleted region harbors 12 OMIM genes, of which POU3F4, CHM, and ZNF711 might have contributed to the patient’s phenotype including hearing loss, poor vision, and intellectual disability." (PMID 28630650, 2017). "This furtherly suggests that ZNF711 gene loss might be an independent cause to mental retardation." (PMID 28630650, 2017). "However, mutations in the ZNF711 coding sequence have been found to be associated with several families that display X-linked inherited mental retardation, suggesting that ZFX family members may be critical mediators of cell proliferation and/or have a role in tissue-specific differentiation." (PMID 32406922, 2020).
choroideremia (2 papers, 2015 to 2021). Choroideremia (CHM) is an X-linked chorioretinal dystrophy characterized by progressive degeneration of the choroid, retinal pigment epithelium (RPE) and retina. "POU3F4 has a proven role in hearing loss and inner ear malformations, ZNF711 has been associated with simple ID and CHM with the choroideremia." (PMID 25821518, 2015).
Hearing impairment (2 papers, 2017 to 2021). A decreased magnitude of the sensory perception of sound. "Interestingly, a large deletion involving CHM and the neighboring POU3F4 and ZNF711 genes has been previously identified in a CHM patient with hearing impairment and developmental disability." (PMID 34440285, 2021).
brain tumor (1 paper, 2018). "This motif was originally identified from ZNF711 ChIP-seq data from the brain tumor cell line SH-SY5Y and from ZFX ChIP-seq data from mouse embryonic stem cells." (PMID 29429977, 2018).
epilepsy (1 paper, 2025). A brain disorder characterized by episodes of abnormally increased neuronal discharge resulting in transient episodes of sensory or motor neurological dysfunction, or psychic dysfunction. "In our familial cohort, we present the first case series of patients with ID and epilepsy, likely caused by a pathogenic variant in the ZNF711 gene, expanding the known clinical spectrum of these variants." (PMID 39852778, 2025). "While additional studies are required to better understand the specific role of ZNF711 variants in the development of epilepsy, it expands the clinical spectrum of ZNF711 variants by highlighting epilepsy as a possible comorbidity." (PMID 39852778, 2025). "Both children carry a hemizygous c.657C > G pathogenic variant in the ZNF711 gene inherited from the maternal side of the family, and their parents have no previous history of epilepsy or neurodevelopmental delays." (PMID 39852778, 2025). "On the contrary, no cases of ZNF711 mutations have been associated with epilepsy." (PMID 39852778, 2025).
leukemia (1 paper, 2019). A malignant (clonal) hematologic disorder, involving hematopoietic stem cells and characterized by the presence of primitive or atypical myeloid or lymphoid cells in the bone marrow and the blood. "Furthermore, our transcription factor binding motif analysis validated that the HVMRs were enriched for motifs with divergent functions, such as ZNF711 for cognitive disability, PBX3 for leukemia and PKNOX1 for adult spermatogenesis." (PMID 31752687, 2019).
ovarian carcinoma (1 paper, 2022). A malignant neoplasm originating from the surface ovarian epithelium. "Furthermore, correlation analysis between 182 DEGs and MEX3A was applied using TCGA ovarian cancer data to obtain 7 DEGs (CSNKE1, OBSL1, DNASE1, ZNF711, TIMELESS, SAMD11, and BCL9) that were positively associated with MEX3A expression (Spearman’s correlation≥0.3)." (PMID 35715407, 2022).
Partington syndrome (1 paper, 2021). A rare neurological condition that is primarily characterized by mild to moderate intellectual disability and dystonia of the hands. "Collectively, these findings suggest that PHF8 and ZNF711 may act as gene modifiers of ARX-disease phenotypes; thus, variants in these NDD genes may contribute to the phenotype variability from West syndrome to Partington syndrome to mild ID caused by ARX polyalanine expansions." (PMID 34356104, 2021).
prostate carcinoma (1 paper, 2020). A carcinoma that arises from epithelial cells of the prostate gland. "However, less than half of the bound promoters show responsiveness to loss of ZFX and ZNF711 in the knockout HEK293T cells or after knockdown of all three family members in 22Rv1 prostate cancer cells (data not shown)." (PMID 32406922, 2020).
cancer (3 papers, 2018 to 2021). A tumor composed of atypical neoplastic, often pleomorphic cells that invade other tissues. "The other 2 members of the ZFX family, ZFY and ZNF711, have not been as well-studied, especially in the cancer field." (PMID 32406922, 2020). "Unlike the ZFX binding pattern in the four cancer cell types, ZNF711 appears to have more cell-type–specific binding sites." (PMID 29429977, 2018).
tumor (3 papers, 2009 to 2021). "SBSN, ZNF-711 and G6PD have not previously been associated with tumor specific expression or carcinogenesis." (PMID 19997593, 2009).
ZNF711 also shares sentences with these, for which no sentence is quoted: Arthritis (2 papers); autism (2); Angelman syndrome (1); breast carcinoma (1); developmental disability (1); fragile X syndrome (1); generalized epilepsy (1); Kabuki syndrome (1); language delay (1); lymphoma (1); malaria (1); ovarian tumor (1); Rett syndrome (1); schizophrenia (1); Seizure (1); Stroke (1); West syndrome (1).